MIR4437 (microRNA 4437)
Synonyms: hsa-mir-4437; mir-4437
Gene: MicroRNA gene on chromosome 2 (181,305,593 to 181,305,652, reverse strand). Ensembl gene ENSG00000266705.
Homologues: Orthologues: chimpanzee MIR4437 (100% identical).